CD4 (CD4 molecule)
Diseases named in the same sentence as CD4 in open-access papers (continued):
Sharing a sentence is not in itself a finding about the gene and the disease.
Obesity (continued). "These inflammatory cells likely contribute to the pathology of obesity-induced lymphatic dysfunction since inhibition of inflammatory reactions with topical IL-2 inhibitors or genetic deficiency of CD4+ T cells decreased the severity of lymphatic injury in obese animals." (PMID 32268536, 2020). "Importantly, one hallmark of obesity-induced AT inflammation is the increased CD8+ to CD4+ T-cell ratio." (PMID 32973799, 2020). "Diet-induced obesity has also been associated with altered splenic CD4+ cells, macrophages, and dendritic cells in mice and elevated inflammatory cytokines and risk of mortality; with this, metabolic dysfunction is also seen to be transferable to offspring in murine studies." (PMID 31582905, 2019). "Although total CD4+ T-cell numbers were comparable between the two groups, pregravid obesity was associated with lower numbers of naïve and increased numbers of central memory cells, that was accompanied by decreased homeostatic proliferation within the central memory subset." (PMID 30131724, 2018). "Moreover, pregravid obesity was associated with lower frequency of naïve CD4+ T-cells (p < 0.05), increased frequency of memory CD4+ T-cells (p < 0.01), and a shift towards Th2 cytokine production (p = 0.05)." (PMID 30131724, 2018). "Finally, we have highlighted the therapeutic potential of targeting CD4+ T cells as an effective strategy for the treatment of obesity and its associated metabolic diseases." (PMID 30233575, 2018). "However, a recent study has shown a novel link between obesity-induced lipid accumulation and selective CD4+T lymphocyte loss, suggest a critical role for CD4+ T lymphocytes in the disease progression from NAFLD to HCC30." (PMID 30250040, 2018). "Consequently, CD4+ T-cells have both direct and indirect roles in obesity-associated adipose tissue immunometabolic dysfunction." (PMID 29479350, 2018). "In addition to HAART, raised CD4 count levels have been reportedly associated with obesity in previous studies." (PMID 29769110, 2018). "Obesity is associated with increased insulin levels, which affects CD4+ T cells." (PMID 28651594, 2017). "Interestingly, C18:2 induced cell death in CD4+ T lymphocytes in vivo, suggesting that obesity-induced lipid accumulation promotes disease progression from NAFLD to hepatocellular carcinoma via the selective loss of CD4+ T lymphocytes." (PMID 28852648, 2017). "In contrast to the relatively simple pro-inflammatory role of CD8+ T cells in obesity, the contribution of CD4+ T cells to obesity-associated inflammation and IR is complex, because CD4+ T cells can differentiate into distinct effector T cell populations with opposing functions." (PMID 26366435, 2013). "Reduced obesity in CD4+ T-cell-reconstituted Rag1−/− mice therefore might not associate with Th2 or Treg, but rather with other uncharacterized CD4+ T-cell populations." (PMID 23027613, 2012). "Additionally, both mice with diet-induced obesity and human subjects with obesity demonstrated heightened levels of IL-6, which are predisposing factors in Th17 lineage expansion, consequently leading to an increase in the number of CD4+ cells secreting IL-17." (PMID 39125666, 2024). "In addition to the ART regimen type, factors such as female gender, African descent, older age, longer duration of HIV and ART, high pretreatment HIV viral load, low baseline cluster of differentiation 4 (CD4)+ count, and low physical activity were also linked with overweight and obesity." (PMID 39735593, 2024). "Thus, elevated pSTAT3 in the circulating CD4+ Th17 (and perhaps other helper subsets) in active PsA patients in our study could be partially driven by factors associated with obesity." (PMID 35087513, 2021). "Differential DNA methylation analysis highlights autophagy and immune senescence as potential key mechanisms underpinning this memory of obesity in CD4 T cells." (PMID 42045443, 2026).
Obesity (continued). "Here, we show that obesity imprints CD4 T cells through DNA methylation, leading to a long-time lag, spanning years, before adaptive immune homeostasis is restored after weight loss." (PMID 42045443, 2026). "Multivariable linear models revealed that obesity, CD4 cell counts < 200 cells/ μL, higher hemoglobin level and hematocrit, and higher GAF scores were significantly associated with IHDS score (p < 0.05)." (PMID 42095976, 2026). "Our group and others have shown that chronic CD4+ cell inflammatory reactions play a key role in impaired lymphatic function in lymphedema and obesity." (PMID 40426856, 2025). "During diet-induced obesity in mice, the frequencies of IL-9 + CD4 + T cells and ILC2s and IL-9R expression on macrophages are significantly decreased." (PMID 40962954, 2025). "CellChat analysis of the scRNA‐seq dataset predicted highly altered cDC1/CD4+ T cell interactions in obesity." (PMID 41164009, 2025). "Taken together, during obesity, IL-9 production by CD4 + T cells and ILC2s and IL-9R expression on macrophages are significantly downregulated." (PMID 40962954, 2025). "In contrast, T-cell populations in both abdominal and femoral SAT were unaffected by the age of obesity onset at baseline; however, CD3+CD4+ T cells increased after weight loss only in those with AO." (PMID 40831565, 2025). "Among individuals with CD4 counts ≤ 500 cells/μL, the prevalence of obesity was significantly lower in the LTBI group compared to the controls (p = 0.017)." (PMID 41305316, 2025). "In humans, CD4+ T cells also play a pathogenetic role in obesity and insulin resistance; naïve CD4+ T cells and Tregs are reduced while the number of NK cells is increased." (PMID 39940640, 2025). "The absolute counts confirmed the reduction of CD4− iNKT cells in individuals with obesity compared to lean individuals." (PMID 41000378, 2025). "Basal cytokine production (IFN-γ, TNF-α, IL-4) was also significantly and specifically increased in CD4− (CD8+) iNKT cells from individuals with obesity compared to lean individuals." (PMID 41000378, 2025). "In contrast, CD8 and CD4 T-cell densities were increased across all compartments in obesity, with the most marked increases in ductal CD8 T-cells." (PMID 40909804, 2025). "Conversely, other studies have reported lower counts of the following immune cells in patients with obesity and/or MS compared to their lean counterparts: a decreased percentage of total lymphocytes, CD4+CD45RA+, CD8+CD45RA+, and B cells (% and cells/μL)." (PMID 41155165, 2025). "Since the receptor NKG2D is known to be mainly expressed on CD4− iNKT cells, this reduction likely reflects the decrease in CD4− iNKT cells in individuals with obesity." (PMID 41000378, 2025). "It has been shown that adiponectin reduces the production of IFN-γ and IL-17 by CD4 T cells in obesity by reducing intracellular glycolysis." (PMID 40282186, 2025). "We further investigated the association between obesity and LTBI within CD4+ T cell stratified subgroups." (PMID 41305316, 2025). "Both CD4+ and CD4− iNKT subsets exhibited impaired IFN-γ production, while obesity tends to predominantly affect TNF-α production in the CD4− subset." (PMID 41000378, 2025). "SAT Treg cells, an anti-inflammatory subset of CD3+CD4+ T cells, are both reduced and less functional in adults with obesity." (PMID 40831565, 2025). "Diet-induced obesity increases ACC1 expression in memory CD4 T cells, driving IL-17 production in vitro and Th17-dependent pathology in vivo." (PMID 39763655, 2024). "While Th1 cells for a long time have been imputed as drivers of tissue inflammation in obesity, more recent studies have found that CD4 T cells from obese VAT are functionally exhausted, with PD-1+ cells endowed with senescent characteristics." (PMID 38380252, 2024). "Elevated leptin levels and the accumulation of unsaturated fatty acids typical of obesity lead to alterations in CD4+ T cells, resulting in their dysfunction and eventual apoptosis." (PMID 39000296, 2024).
Obesity (continued). "Obesity in humans is associated with elevated ACACA expression and IL-17 production from memory CD45RO+ CD4 T cells." (PMID 39763655, 2024). "The CD4+CD8+ Treg cells were decreased only in Class II obesity (0.34% ± 0.17 vs. nOB: 1.1% ± 1.1, p < 0.05)." (PMID 38397455, 2024). "One notable exception is that CD4+ T cells have been shown to memorize obesity and promote weight regain in a mouse model, supporting a causal role of T cells in the development of adiposity." (PMID 38551005, 2024). "With the use of ART, obesity was also more common in PLWH, and CD4+T cell counts increased with normal weight and obesity." (PMID 38666515, 2024). "CD4+ T cell infiltration in adipose tissue correlates with body mass index and obesity-related exhaustion." (PMID 38542220, 2024). "CD4+ helper T cell 1 (Th1) promotes inflammation in obesity development and increases in number, while CD4+ helper T cell 2 (Th2) has an anti-inflammatory role and decreases in number." (PMID 39456156, 2024). "CD4+ Tsen levels correlated positively with age, obesity, and age-related comorbidities like cardiovascular diseases and chronic obstructive pulmonary diseases." (PMID 38377029, 2024). "Only when the degree of obesity had a corresponding impact on the patient's immune status, such as greater infiltration levels of memory B cells and activated CD4 T cells, would it greatly influences the patient's prognosis." (PMID 39170242, 2024). "CD4+ T-cells, particularly regulatory T-cells (Tregs), are crucial for controlling inflammation and metabolic processes in obesity." (PMID 38279278, 2024). "This study underscores that CD4+ T-cell KLF10 is a key regulator of obesity and insulin resistance by modulating Treg metabolism and mobilization." (PMID 38279278, 2024). "Participants with obesity presented a decrease in the percentage of CD4+ regulatory T cells measured in whole blood (OB: 0.67% ± 0.3 vs. nOB: 0.89% ± 0.3, p < 0.05)." (PMID 38397455, 2024). "Participants with a CD4 cell count ≥ 500 cells/mm3 were 3.6 times more likely to experience overweight and obesity compared with those with a CD4 cell count < 500 cells/mm3." (PMID 39735593, 2024). "CCR5−CCR6− Th cells comprised approximately 52% ± 9.0 of the CD4+ T cells in the nOB group, while in OB groups they comprised 39% ± 9.8 of the CD4+ T cell compartment (p < 0.05), even among obesity classes and metabolic groups." (PMID 38397455, 2024). "In Sirt6 LKO mice with obesity background, we have found reduced CD4+ and CD8+ T cells in the liver." (PMID 38332150, 2024). "The study concluded that immune cells can retain a memory of obesity and store it in CD4 + T-cells, which ultimately results in inevitable weight regain." (PMID 38317257, 2024). "Similar to Th1-like Treg, CD4+ Tfr showed a higher percentage of cells with a Th1-like phenotype within Class III obesity and IRn, when compared to nOB (p < 0.05)." (PMID 38397455, 2024). "In the class 1 and 2 obesity group, a decrease in the FFM percentage was associated with a decrease in CD4+CD45RO+ T lymphocytes and an increase in CD4+CD45RA+ T lymphocytes in peripheral blood." (PMID 37334132, 2023). "Like the findings in mice models, the number of CD4+Foxp3+ Treg is decreased in adipose tissue and peripheral blood from adult individuals with obesity and diabetes." (PMID 39872860, 2023). "We observed that as the degree of obesity increased, CD4+ lymphocytes and CD4+CD62- T lymphocytes also increased." (PMID 37334132, 2023). "Interferon-γ (IFN-γ)–expressing CD4+ cells increase in obesity, and IFN-γ deletion improves obesity-induced IR and lowers macrophage infiltration in adipose tissue." (PMID 39872860, 2023). "Prior to LVAD implantation, all groups showed high proportions of CD4+ T cells (normal weight: 64.4 ± 20.6%; pre-obesity: 65.2 ± 16.5%; obesity: 68.5 ± 9.2%, p = 0.74)." (PMID 37885885, 2023).
Obesity (continued). "Obesity complicates classic T helper 2 cells (Th2) inflammation; e.g., in obesity, eosinophilic airway inflammation is altered and eosinophil transport into the airway lumen is altered, and obesity biases CD4+T cells toward T helper 1 cell (Th1) polarization." (PMID 38292857, 2023). "Apart from alterations in the monocyte compartment, differences in the CD4+ T cell population characterized by decreased naïve T cells and increased memory T cells have been described in obesity." (PMID 37266430, 2023). "Moreover, reduced tumor infiltration of CD4+ T cells caused by ROS burst might also impair immunotherapy targeting liver tumors, suggesting that overcoming FA-induced impairment could be a potential strategy for obesity-related HCC." (PMID 37266440, 2023). "Obesity usually increases circulating CD4+ T cell levels via leptin-mediated upregulation of major histocompatibility complexes-II (MHC-II, 80)." (PMID 37266440, 2023). "It should be emphasized that most lymphocytes present in colostrum are T lymphocytes and that CD4+T lymphocytes are essential cells that have the potential to alter the markers of inflammation and are reduced in obesity." (PMID 36768983, 2023). "CD4+ T cells contribute to the inflammatory state in both, HF and obesity, and promote the generation of effector CD8+ T cells, for example, via enhanced antigen presenting cell-mediated IL-6 and TNF-α production." (PMID 37885885, 2023). "Nevertheless, regarding adaptive immunity, CD4+ T cells seem to play a more important role in obesity and IR." (PMID 39872860, 2023). "In obesity, CD4+ T cells were activated by adipocytes leading to T cell differentiation, expansion and cytokine production that contribute to the chronic inflammatory process in adipose tissue." (PMID 37885885, 2023). "Activated or decreased CD4+ T cells in adipose tissue play a vital role in maintaining the pro-inflammatory state in obesity." (PMID 37761835, 2023). "Still according to our previous study, in CD4+ T cell cultures from lean AA patients, obesity-related leptin concentration enhanced Th2- and Th17-related cytokine production and impaired Treg function in response to polyclonal activators." (PMID 37954580, 2023). "Since CD4+ T cell metabolism has been previously shown to be altered in obesity, we sought to characterize the metabolic phenotype of CD4+ T cells from T cell-specific leptin receptor knockout mice versus littermate control mice on either NC or HFD." (PMID 37276236, 2023). "Immunomodulation:- ↑ Cell-mediated immune response, CD4+ lymphocyte population and CD4+:CD8+ ratio.Obesity:- ↓ Serum total- and LDL- cholesterol." (PMID 37954670, 2023). "The main risk factors influencing its occurrence are a low baseline CD4/CD8 ratio, overweight and obesity, and the use of AZT or LPV/r in the cART regimen." (PMID 36823632, 2023). "Some investigations have shown the association between CD4+ T cells and the progression of obesity and obesity-related diseases, suggesting the role of CD4 in controlling immune and adipose tissue." (PMID 37761835, 2023). "In obesity, there is evidence that interferon gamma-producing pro-inflammatory CD4‐positive Th1 cells are increased, whereas anti‐inflammatory CD4‐positive Th2 and Treg cells are reduced." (PMID 36376974, 2022). "Accordingly, this study aimed to clarify how obesity affects the immunosurveillance function and anti-tumor activity of CD4+ T cells in CRC using mouse models." (PMID 36611881, 2022). "This indicates that the number and PD-1 expression of CD8+ T cells in the tumors are affected not only by obesity but also by CD4+ T cells." (PMID 36611881, 2022). "An adipose tissue from patients with obesity and T2D produced specific enrichment of CD4+ T cells for IL-17 and IL-22, which is pathologically relevant to obesity-induced T2D." (PMID 36225181, 2022). "Compared to control, both DCM and obesity groups had a higher proportion of resting memory CD4 and naive T cells, as well as resting NK cells." (PMID 36547458, 2022).
Obesity (continued). "Further, obesity increases the frequency of both CD4 and CD8 T cells and the reduction of CD8 T cells significantly lowers the M1 macrophages." (PMID 36517853, 2022). "Our results also suggest that, in the obesity-associated TIME, the reduced cytotoxic activity of CD8+ T cells was caused by CD4+ T cell dysfunction." (PMID 36611881, 2022). "Nonetheless, obesity‐related dose of leptin elevated not only the release of IL‐6 and IL‐17, but also IL‐5 and IL‐13 by CD4+ T cells in lean‐derived cell cultures from patients." (PMID 35734271, 2022). "Further research has shown the influence of elevated O-GlcNAc in CD4+ T cells in mediating a pro-inflammatory Th17 response in an obesity mouse model." (PMID 36776401, 2022). "- Higher abundance of CD4+ (Th1, Th17) and CD8+ T-cells in both subcutaneous and visceral adipose tissues in obesity associate with insulin resistance." (PMID 35574032, 2022). "CD4+ T cell-specific KLF10 deficiency leads to inflammation in adipose tissue, IR, obesity and the onset of NAFLD with impaired Treg accumulation." (PMID 35912096, 2022). "A similar mechanism can be assumed for CD4+ T cells in obesity because our results are compatible with these reports." (PMID 36611881, 2022). "At the same time, EOMES-positive CD4 + T cells proved to be a risk T cell subset of RA; Studies have also discussed the molecular role of RUNX1 in obesity and related metabolic diseases." (PMID 35874719, 2022). "As previously reported, obesity resulted in a significant decrease in the percentage of circulating CD4+CD25+Foxp3+ regulatory T cells but a decreased proportion of peripheral blood monocytes (F4/80+ CD11b+ and CD11b+) compared to lean controls." (PMID 35472214, 2022). "The frequency of CD4+ cells in the subgroup of COVID‐19 patients with obesity was significantly decreased in the severe group as compared to the non‐severe group." (PMID 35837843, 2022). "TGFβ3 secretion was also found to be decreased in a genetic model of mice with CD4+ T cell-specific KLF10 knockout in vitro and in vivo, and these mice have a predisposition to obesity, insulin resistance, and fatty liver." (PMID 36425072, 2022). "We further established CD4+ T cell-depleted HFD-fed model mice, which showed reduced tumor infiltration, increased PD-1 expression in CD8+ T cells, and obesity-induced acceleration of tumor growth in a CD4+ T cell-dependent manner." (PMID 36611881, 2022). "Among those tested for SARS-CoV-2, PLWH who tested positive had lower rates of chronic renal disease (11% versus 12%, p = 0.030), higher rates of obesity (40% versus 33, p = 0.046), and higher median nadir CD4 + T lymphocyte counts (533 versus 413, p = 0.036)." (PMID 37063094, 2022). "Analysing by manifestations, lower levels of baseline activated T CD4+ lymphocytes (CD69) were observed in patients with obesity (1 ± 0.2 vs. 2.4 ± 0.7%; p = 0.076) and metabolic syndrome (1 ± 0.2 vs. 2.2 ± 0.5%; p = 0.039)." (PMID 35165326, 2022). "Adiponectin has been shown to limit pro-inflammatory responses in obesity by limiting IFN-γ and IL-17 producing CD4+ T cells in obesity." (PMID 36544761, 2022). "CD4+ T cells (Th1) drive type 1 cytokine release (as IFN-γ) in ATs of individuals with obesity, amplifying tissue chronic inflammation." (PMID 36033972, 2022). "Overweight and obesity were significantly higher among hypertensive, with higher recent CD4 counts and abdominal obese ART patients." (PMID 35821078, 2022). "We found that in HFD-fed mice, the CD4+ T cells in the peripheral blood were reduced in number and more exhausted over time with the development of obesity." (PMID 36611881, 2022). "Based on these findings, we concluded that the reduced number and anti-tumor immune dysfunction of CD4+ T cells accelerated tumor growth due to HFD-induced obesity." (PMID 36611881, 2022).